SVOP (SV2 related protein)
Synonyms: DKFZp761H039; SLC22B4
Tractability: Small molecule: it belongs to a druggable protein family. Antibody: UniProt predicts a signal peptide or a membrane-spanning region. PROTAC: its protein half-life has been measured.
Gene: Protein-coding gene on chromosome 12 (108,907,741 to 109,021,068, reverse strand). Ensembl gene ENSG00000166111.
Subcellular location: Cytoplasmic vesicle, secretory vesicle, synaptic vesicle membrane
Gene Ontology:
Molecular function: protein binding; transmembrane transporter activity
Biological process: transmembrane transport
Cellular component: synaptic vesicle; basal plasma membrane; membrane; synaptic vesicle membrane
Genetic constraint (gnomAD): Loss-of-function variants: 12 observed, 59.53 expected, observed/expected ratio (o/e) 0.2, 90% interval 0.13 to 0.33. The upper end of that interval is the gene's LOEUF score, 0.33, which puts it in group 1 of 6, group 1 being the genes least tolerant of losing a copy. Missense variants: 408 observed, 566.15 expected, observed/expected ratio (o/e) 0.72, 90% interval 0.66 to 0.78. Synonymous variants: 229 observed, 230.21 expected, observed/expected ratio (o/e) 0.99, 90% interval 0.89 to 1.11.
Homologues: Orthologues: chimpanzee SVOP (98% identical), guinea pig SVOP (97% identical), rat Svop (96% identical), mouse Svop (96% identical), pig SVOP (95% identical), tropical clawed frog svop (87% identical), zebrafish svopa (77% identical), dog SVOP (74% identical), macaque SVOP (68% identical), rabbit SVOP (57% identical), Caenorhabditis elegans svop-1 (49% identical), Drosophila melanogaster CG4324 (42% identical). Paralogues in human: SVOPL (34% identical), SLC22A1 (24% identical), SLC22A7 (24% identical), SLC22A2 (23% identical), SLC22A3 (22% identical), SLC22A5 (22% identical), SLC22A8 (22% identical), SLC22A4 (22% identical), SLC22A13 (21% identical), SLC22A15 (21% identical), SLC22A6 (21% identical), SLC22A11 (20% identical), and 10 more.
Diseases named in the same sentence as SVOP in open-access papers:
SVOP is named in the same sentence as 5 diseases in open-access papers, as found by Europe PMC text mining. Sharing a sentence is not in itself a finding about the gene and the disease. The quoted sentences say what the papers report.
glioblastoma (2 papers, 2022 to 2023). The most malignant astrocytic tumor (WHO grade IV). "SVOP aberrant methylated played an important role in regulation of nervous system, and was associated with progression of glioblastoma." (PMID 35794546, 2022).
glioma (2 papers, 2021 to 2022). A benign or malignant brain and spinal cord tumor that arises from glial cells (astrocytes, oligodendrocytes, ependymal cells). "SVOP and IGFBP2 may play different functions in different grades of gliomas and follow-up studies in these contexts are in progress." (PMID 35493457, 2022).
SVOP also shares sentences with these, for which no sentence is quoted: Alzheimer disease (2 papers); colorectal cancer (1); dementia (1).